CLN5 (CLN5 lysosomal BMP synthase)
Description:
[Bis(monoacylglycero)phosphate synthase CLN5, secreted form]: Catalyzes the synthesis of bis(monoacylglycero)phosphate (BMP) via transacylation of 2 molecules of lysophosphatidylglycerol (LPG). BMP also known as lysobisphosphatidic acid plays a key role in the formation of intraluminal vesicles and in maintaining intracellular cholesterol homeostasis. Can use only LPG as the exclusive lysophospholipid acyl donor for base exchange and displays BMP synthase activity towards various LPGs (LPG 14:0, LPG 16:0, LPG 18:0, LPG 18:1) with a higher preference for longer chain lengths. Plays a role in influencing the retrograde trafficking of lysosomal sorting receptors SORT1 and IGF2R from the endosomes to the trans-Golgi network by controlling the recruitment of retromer complex to the endosomal membrane. Regulates the localization and activation of RAB7A which is required to recruit the retromer complex to the endosomal membrane. Exhibits palmitoyl protein thioesterase (S-depalmitoylation) activity in vitro and most likely plays a role in protein S-depalmitoylation.
Tractability: Antibody: UniProt predicts a signal peptide or a membrane-spanning region. PROTAC: ubiquitination databases record sites on it; its protein half-life has been measured.
Gene: Protein-coding gene on chromosome 13 (76,990,660 to 77,019,143, forward strand). Ensembl gene ENSG00000102805.
Subcellular location: Lysosome (Bis(monoacylglycero)phosphate synthase CLN5, secreted form); Membrane (Bis(monoacylglycero)phosphate synthase CLN5)
Gene Ontology:
Molecular function: bis(monoacylglycero)phosphate synthase activity; D-mannose binding; long-chain fatty acyl-CoA hydrolase activity; palmitoyl-(protein) hydrolase activity; protein binding; hydrolase activity, acting on glycosyl bonds
Biological process: brain development; lysosomal lumen acidification; neurogenesis; positive regulation of GTP binding; protein maturation; retrograde transport, endosome to Golgi; lysosome organization; neuron maturation; protein catabolic process; macromolecule depalmitoylation
Cellular component: endoplasmic reticulum; extracellular exosome; Golgi apparatus; lysosomal membrane; lysosome; membrane; perinuclear region of cytoplasm; cytosol; vacuolar lumen
Genetic constraint (gnomAD): Loss-of-function variants: 31 observed, 34.94 expected, observed/expected ratio (o/e) 0.89, 90% interval 0.67 to 1.2. The upper end of that interval is the gene's LOEUF score, 1.2, which puts it in group 5 of 6, group 1 being the genes least tolerant of losing a copy. Missense variants: 427 observed, 442.86 expected, observed/expected ratio (o/e) 0.96, 90% interval 0.89 to 1.04. Synonymous variants: 151 observed, 156.12 expected, observed/expected ratio (o/e) 0.97, 90% interval 0.85 to 1.11.
Gene-disease validity (ClinGen):
ClinGen rates the evidence that CLN5 causes each of these diseases.
neuronal ceroid lipofuscinosis (autosomal recessive): Definitive.
Homologues: Orthologues: chimpanzee CLN5 (98% identical), macaque CLN5 (94% identical), pig CLN5 (84% identical), dog CLN5 (83% identical), rabbit CLN5 (81% identical), guinea pig CLN5 (78% identical), rat AABR07019209.2 (72% identical), mouse Cln5 (72% identical), rat AABR07008608.1 (71% identical), tropical clawed frog cln5 (61% identical), zebrafish cln5 (52% identical).
Diseases named in the same sentence as CLN5 in open-access papers:
CLN5 is named in the same sentence as 59 diseases in open-access papers, as found by Europe PMC text mining. Sharing a sentence is not in itself a finding about the gene and the disease. The quoted sentences say what the papers report.
neuronal ceroid lipofuscinosis (22 papers, 2008 to 2025). "Mutations in the CLN5 gene cause the fatal, pediatric, neurodegenerative disease CLN5 neuronal ceroid lipofuscinosis." (PMID 37942487, 2023). "CLN5 disease (MIM: 256731) represents a rare late-infantile form of neuronal ceroid lipofuscinosis (NCL), caused by mutations in the CLN5 gene that encodes the CLN5 protein (CLN5p), whose physiological roles stay unanswered." (PMID 35681535, 2022). "CLN5 disease is a rare form of late-infantile neuronal ceroid lipofuscinosis (NCL) caused by mutations in the CLN5 gene that encodes a protein whose primary function and physiological roles remains unresolved." (PMID 32257390, 2020). "Mutations in CLN5 lead to neuronal ceroid lipofuscinosis, a group of inherited neurodegenerative disorders that mainly affect children." (PMID 24058541, 2013). "Mutations in CLN5 cause a subtype of neuronal ceroid lipofuscinosis (NCL) called CLN5 disease." (PMID 36437924, 2022). "For instance, neuronal ceroid lipofuscinosis (NCL) has been linked to mutations of genes related to lysosomal function, including GRN (granulin), CTSD (cathepsin D) and CLN5 (ceroid lipofuscinosis neuronal protein 5)." (PMID 41387918, 2025). "CLN5 neuronal ceroid lipofuscinosis (NCL, Batten disease) is a rare, inherited fatal neurodegenerative disorder caused by mutations in the CLN5 gene." (PMID 37614821, 2023). "While variants in genes associated with neuronal ceroid lipofuscinosis (CLN3 (OMIM 607042), CLN5 (OMIM 608102), and MFSD8/CLN7 (OMIM611124)) typically lead to severe neuronal dysfunction and lysosomal storage in neurons and the peripheral tissues, some variants present with isolated retina disease." (PMID 35226187, 2022). "Based on our pilot data with a small sample size, several candidate conditions such as 21-Hydroxylase deficient congenital adrenal hyperplasia, Krabbe’s disease, and CLN5-related neuronal ceroid lipofuscinosis should be further investigated in the Chinese population." (PMID 33805278, 2021). "To gain insights into the molecular pathogenesis of the various NCLs we have recently generated mouse models of the Infantile Neuronal Ceroid Lipofuscinosis (INCL, CLN1) and the Finnish variant form of Late Infantile Neuronal Ceroid Lipofuscinosis (vLINCLFin, CLN5)." (PMID 18371231, 2008). "The article contains raw and analyzed data related to the research article “Neuronal ceroid lipofuscinosis genes, CLN2, CLN3, CLN5 are spatially and temporally co-expressed in a developing mouse brain”." (PMID 27508227, 2016). "Neuronal ceroid lipofuscinosis genes: CLN1, CLN2, CLN3, CLN5 were examined in neuronal tissue during mouse brain development." (PMID 27508227, 2016).
Batten disease (11 papers, 2015 to 2026). "CLN5 Batten disease, caused by biallelic mutations in CLN5, is a rare, early-onset neurodegenerative lysosomal storage disorder that has no cure and lacks validated biomarkers, hindering accurate diagnosis and assessment of therapeutic response." (PMID 41890119, 2026). "With similar pathologies to those observed in humans and a conserved CLN5 sequence, these models are key to understanding the underlying biology of CLN5 Batten disease." (PMID 33792748, 2021). "CLN5 interacts with other CLN proteins associated with Batten disease to maintain lysosomal homeostasis." (PMID 34680045, 2021). "Understanding the long-elusive function(s) of CLN5 and how mutations cause Batten disease will not only shed much-needed light on Batten disease mechanisms but will also reveal the significance of lysosomal function in neuronal homeostasis." (PMID 33792748, 2021). "One report suggested that impaired mitophagy and multiple defects in the activity of respiratory chain enzymes in the cerebral cortex is also associated with CLN5 Batten disease, suggesting mitochondrial defects in addition to the lysosomal impairment." (PMID 33792748, 2021). "Knowing how CLN5 mutations cause Batten disease and having the right models and readouts to test efficacy is vital." (PMID 33792748, 2021). "Primary cultures of neurons, neuroblasts, astrocytes and microglia derived from CLN5 sheep (discussed under “Sheep” in “Large animal models” section) exhibit hallmark features of Batten disease including a decrease in lysosomal acidity, autophagy and endocytosis." (PMID 33792748, 2021). "With CLN5 expression being fairly high in several peripheral tissues, and the effect of loss of CLN5 still unknown in most of these tissues, a cautious approach needs to be taken while developing therapies to treat CLN5 Batten disease." (PMID 33792748, 2021). "Cellular models of CLN5 Batten disease have been invaluable tools to understand the underlying molecular pathology and range from ancient social amoeba Dictyostelium discoideum, to immortalised cell lines, patient derived fibroblasts and iPSCs and primary neural cultures from mice and sheep." (PMID 33792748, 2021). "These primary cultures are excellent tools to study CLN5 pathophysiology, however, none of these studies have commented on whether these cultures exhibit hallmark features of CLN5 Batten disease." (PMID 33792748, 2021). "Translating these results towards clinical utility, we demonstrate BMP and LPG to be accessible biomarkers for CLN5 Batten disease in both plasma and dried blood spots, enabling early diagnosis and patient screening." (PMID 41890119, 2026). "Another Batten disease–related protein CLN5 was recently identified as a lysosomal enzyme that synthesizes BMP using two LPG molecules." (PMID 39970228, 2025). "MRI is a clinically relevant outcome measure used here to complement a wider preclinical study assessing a novel dual‐route administration gene therapy for CLN5 Batten disease." (PMID 40181626, 2025). "In this comprehensive review, we have summarised and critiqued existing literature on CLN5 and have discussed the missing pieces of the puzzle that need to be addressed to develop an efficient therapy for CLN5 Batten disease." (PMID 33792748, 2021). "Histological studies characterising CLN5 Batten disease used human fibroblasts from affected individuals to describe key pathologies of CLN5 Batten disease, including accumulation of intralysosomal inclusion bodies." (PMID 33792748, 2021). "Like other cellular models, primary cultures are not able to fully recapitulate the human phenotype and cannot be used to study CLN5 Batten disease at the organism level." (PMID 33792748, 2021). "In fibroblasts derived from CLN5 Batten disease patients, the lysosomal pH is significantly higher than control fibroblasts, without changing the cytoplasmic pH." (PMID 33792748, 2021).
Batten disease (continued). "A characteristic pathology in CLN5 Batten disease is the defects in lysosomes, leading to neuronal dysfunction." (PMID 34680045, 2021). "Since the discovery of mutations in vLINCL families in 1998, CLN5 has been intensively studied both to understand its function and its potential as a therapeutic for CLN5 Batten disease." (PMID 33792748, 2021). "Life expectancy for children with CLN5 mutations is between ten and thirty years, and there is currently no cure or approved treatment for CLN5 Batten disease." (PMID 34680045, 2021). "These phenotypes have also been confirmed in animal models of CLN5 Batten disease, discussed in section “Tissue expression of CLN5”." (PMID 33792748, 2021). "Later studies have reported atypical phenotypes in infantile, juvenile and adult forms of CLN5 Batten disease." (PMID 33792748, 2021). "Although Dictyostelium does not have a nervous system, cells that lack Cln5 show accumulation of ASM and autophagic vacuoles, pathologies seen in human CLN5 Batten disease." (PMID 33792748, 2021). "We highlighted the naturally occurring CLN5 ovine model of Batten disease as an excellent example of how a large animal can not only be used in the identification of novel disease determinants, but also in the development of potential therapeutics." (PMID 28378063, 2017). "Gross neuropathological changes were analyzed in complete sagittal sections of late stage ovine CLN5 Batten disease." (PMID 26664787, 2015). "Gross neuropathological analysis of CLN5 Batten disease sheep and controls was used alongside postmortem MRI imaging to identify affected brain regions." (PMID 26664787, 2015). "Additionally, lysosomal lysates from murine models of CLN5 Batten disease lack the ability to synthesize BMP from its precursor LPG, establishing CLN5 as the main BMP synthase in vivo." (PMID 41890119, 2026). "Over 5 assessments from 5 to 18 months, sheep with CLN5 Batten disease who received moderate‐dose scAAV9/oCLN5 gene therapy pre‐symptomatically exhibited “control‐like” patterns of brain change, strikingly different from the accelerated pattern of atrophy exhibited by untreated affected sheep." (PMID 40181626, 2025). "A second IND-enabling study in sheep has subsequently shown that combined ocular and brain-directed gene therapy simultaneously halt neurological and retinal disease in ovine CLN5 Batten disease, prompting clinical translation of dual ICV and IVT administration for this disease." (PMID 37614821, 2023). "Furthermore, microglial activation and astrocytosis have been shown in CLN5 Batten disease patients, especially in regions where neuronal demise was more prominent." (PMID 33792748, 2021). "CLN5 Batten disease is ultra-rare and as such models are essential in establishing treatments." (PMID 33792748, 2021). "Both CLN5 mouse and sheep models provide strong face validity for aspects of disease progression and sheep have already proved useful in development of a gene therapy strategy for CLN5 Batten disease." (PMID 33792748, 2021). "Fibroblasts from a CLN5 patient were reprogrammed via expression of SOX2, OCT3/4, KLF4 and MYC to generate the CLN5Y392* (New RefSeq sequence: Y343*) iPSC line, the predominant mutation in CLN5 Batten disease." (PMID 33792748, 2021). "A more comprehensive quantitative proteomics approach in human neurons is required to learn about the interacting partners of CLN5 that may address the molecular phenotypes of CLN5 Batten disease." (PMID 33792748, 2021). "Understanding CLN5 function not only has the potential for treatments of CLN5 Batten disease." (PMID 33792748, 2021). "Hence, targeting multiple cell types is key for developing a treatment or cure for CLN5 Batten disease." (PMID 33792748, 2021). "Below we describe cellular models used in the study of CLN5 Batten disease." (PMID 33792748, 2021). "Sheep and mouse models of CLN5 Batten disease also show autophagy impairment." (PMID 33792748, 2021).
Batten disease (continued). "Whether a similar improvement of disease phenotype in CLN5 Batten disease is possible by enhancing TFEB-mediated lysosomal gene activation needs further investigation." (PMID 33792748, 2021). "A variety of immortalised cell types have been used in the study of CLN5 Batten disease." (PMID 33792748, 2021). "We therefore investigated whether molecular regulators of synaptic pathophysiology, previously identified in Drosophila and mouse models, are similarly present and modified in the brain of sheep with CLN5 Batten disease." (PMID 26664787, 2015). "Hence, further research on metal transporters might reveal valuable information on metal homeostasis in CLN5 Batten disease." (PMID 33792748, 2021). "Among the CLN lysosomal proteins affected in Batten disease (CLN1, 2, 3, 5, 7, 10, 12, 13), CLN5 plays a role in maintaining an acidic environment in the lysosomes, a critical feature for a functional lysosome." (PMID 33792748, 2021). "Despite different cellular localisations of mature lysosomal CLN5 and the ER-resident CLN6, there are similar manifestations of brain pathologies between CLN5 and CLN6 Batten disease." (PMID 33792748, 2021). "As is the case for many forms of Batten disease, the lack of knowledge surrounding CLN5 function severely hampers the development of prospective therapies." (PMID 33792748, 2021). "To date, there is no approved targeted treatment or cure for CLN5 Batten disease." (PMID 33792748, 2021). "Furthermore, the CLN5-deficient human neurons also showed impaired lysosomal movement—a phenotype that has never been reported in CLN5 Batten disease." (PMID 34680045, 2021).
CLN5 disease (8 papers, 2017 to 2023). "Recessive mutations in CLN5 are associated with neuronal ceroid lipofuscinosis-5, a syndrome characterized by ataxia, seizures, myoclonus, visual impairment and cognitive/motor decline." (PMID 35216494, 2022). "Since CLN5 disease is a lysosomal storage disorder, it is reasonable to assume increased autophagy is a compensatory effect in CLN5-deficient cells." (PMID 30655561, 2019). "We found that the basal level of LC3-II was elevated in both CLN5 disease patient fibroblasts and CLN5-deficient HeLa cells." (PMID 30655561, 2019). "Mutations in CLN5 primarily cause a late infantile-onset form of NCL known as CLN5 disease." (PMID 34870700, 2021). "Longitudinal neuroimaging indicated a halt or slowing in the stereotypical brain atrophy of ovine CLN5 disease and four of these sheep maintained intracranial volumes in the range of healthy CLN5+/− controls before declining slowly over time." (PMID 37614821, 2023). "In urine obtained from CLN5 disease sheep, effects on pathways related to carbohydrate metabolism were observed, which aligns with the glycoside hydrolase activity of CLN5." (PMID 34870700, 2021). "Next, to further investigate the relationship between IL-1β and neurogenesis in CLN5 disease, we treated WT and Cln5-KO NPCs with recombinant IL-1β, or with an IL-1β blocking antibody." (PMID 28733362, 2017). "For example, in CLN5 disease if only inner retinal cells were corrected through intravitreal therapy they could secrete functional CLN5 protein to other retinal cells, a mechanism known as cross-correction." (PMID 35256654, 2022).
Brain atrophy (6 papers, 2018 to 2025). Partial or complete wasting (loss) of brain tissue that was once present. "In contrast, CLN5−/− sheep share the main neuropathological features of the human disease, including progressive brain atrophy and loss of vision at approximately 11 months of age." (PMID 37942487, 2023). "Affected animals exhibit a human CLN5 disease-like phenotype including progressive brain atrophy and loss of vision from 11 to 12 months of age, and a shortened life span of <22 months." (PMID 37614821, 2023). "Total CSF volume, which typically increases with brain atrophy, remained relatively stable in control CLN5+/− animals (0.06 cm3/month), but increased dramatically by an average of 7.7 cm3 (0.5 cm3/month) in untreated CLN5−/− animals." (PMID 40181626, 2025). "Computed tomography scanning and reconstruction verify that brain atrophy ovine CLN5 NCL originates in the occipital lobes with subsequent propagation throughout the whole cortex and these regional differences are reflected in the ICV loss." (PMID 30136763, 2018). "Although a CLN5 exon 3 knock-out mouse model has provided insights into the spatiotemporal expression of CLN5 in the central nervous system (CNS), these mice lack the severe brain atrophy characteristic of the sheep and human diseases." (PMID 37942487, 2023). "Intracerebroventricular (ICV) administration of an adeno-associated virus serotype 9 (AAV9) carrying CLN5 was able to prevent or halt brain atrophy and cognitive decline in both pre- and post-symptomatic CLN5−/− sheep, and delay but not prevent loss of vision." (PMID 35242840, 2022). "Early symptomatic treated sheep had intracranial volumes similar to, or less than, untreated CLN5−/− sheep prior to ICV injection, yet post-injection brain atrophy was significantly slowed." (PMID 37614821, 2023). "Using these clinically relevant outcome measures has highlighted that a moderate dose of ICV gene therapy given to CLN5‐affected sheep at a pre‐symptomatic disease stage is not sufficient to completely halt brain atrophy." (PMID 40181626, 2025). "Overall, ventricular enlargement was more pronounced in CLN5−/− animals than in CLN6−/− animals, which may indicate a differing pattern of brain atrophy in the different types of ovine NCL." (PMID 30136763, 2018).